ADAMTS9 (ADAM metallopeptidase with thrombospondin type 1 motif 9)
Diseases named in the same sentence as ADAMTS9 in open-access papers (continued):
Sharing a sentence is not in itself a finding about the gene and the disease.
squamous cell carcinoma (1 paper, 2024). A carcinoma arising from squamous epithelial cells. "It was observed that both adenocarcinoma (p = 0.0154) and squamous cell carcinoma (p < 0.0001) exhibited a lower expression of the ADAMTS9 gene compared to normal lung tissue." (PMID 38339175, 2024). "However, in contrast to the expression of the ADAMTS9 gene, the expression of the ADAMTS12 gene was overexpressed in tumor tissue, both in adenocarcinoma (p < 0.0001) and squamous cell carcinoma (p < 0.0001)." (PMID 38339175, 2024). "Interestingly, the ADAMTS9 gene expression appeared to have no significant impact on survival duration in patients with squamous cell carcinoma (p = 0.1029)." (PMID 38339175, 2024). "However, similar to ADAMTS9, the ADAMTS12 gene expression did not appear to have any significant effect on survival duration in squamous cell carcinoma (p = 0.3183)." (PMID 38339175, 2024).
squamous cell lung carcinoma (1 paper, 2025). A carcinoma arising from squamous bronchial epithelial cells. "The findings indicate significantly higher ADAMTS6, ADAMTS9, and ADAMTS12 promoter methylation in the tissue affected by cancer compared with normal tissue in patients with squamous-cell lung cancer (p < 0.001)." (PMID 39940703, 2025).
status epilepticus (1 paper, 2021). Status epilepticus is defined as a continuous seizure lasting more than 30 min, or two or more seizures without full recovery of consciousness between any of them. "Following status epilepticus, transcripts of matrix metalloproteinases such as MMP3, ADAMTS5, ADAMTS8, and ADAMTS9 were induced." (PMID 35185464, 2021).
Stroke (1 paper, 2018). Sudden impairment of blood flow to a part of the brain due to occlusion or rupture of an artery to the brain. "We next assessed if the four genes (CCDC71L, PRKAR2B, ADAMTS9, LOXL4) identified through colocalization of cIMT/carotid plaque with tissue-specific eQTLs also showed evidence for colocalization with CHD and stroke traits." (PMID 30510157, 2018).
tumor (29 papers, 2008 to 2025). "A disintegrin‐like and metalloprotease with thrombospondin type 1 motif 9 (ADAMTS9) encodes a zinc metalloprotease that has been shown to function as a tumour suppressor in other cancer models leading to downregulation of the AKT/mTOR pathway." (PMID 40135438, 2025). "We also observed a significant increase in ADAMTS9 expression in tumors compared with adjacent non tumor tissue and an association between high expression and worse prognosis." (PMID 33805340, 2021). "Although ADAMTS-9 has been linked to VCAN proteolysis in various contexts, including embryogenesis and cardiac and aortic anomalies, its role in the tumor microenvironment remains underexplored." (PMID 39682243, 2024). "In brief, METTL3 overexpression in GC promoted the m6A modification of ADAMTS9, a tumor-suppressor gene, and epigenetically prevented its transcription in a YTHDF2-dependent manner." (PMID 35574388, 2022). "We also subcutaneously inoculated BGC-823 cells with ADAMTS9 overexpression and the control ones into six male Balb/c nude mice and detected growth of the tumor masses within 34 days." (PMID 33931579, 2021). "ADAMTS9 is an additional tumor suppressing protein, which was markedly decreased in esophageal, nasopharyngeal, gastric, colorectal, pancreatic cancer as well as multiple myeloma." (PMID 33931579, 2021). "Meanwhile, the weights of the harvested tumor masses demonstrated that ADAMTS9 inhibited the proliferation of BGC-823 cells in vivo." (PMID 33931579, 2021). "We found ACAP1, IFIT3 and TAP1 were upregulated in tumor samples, while ADAMTS9, COL6A2, FBN1 and FSTL1 were downregulated in tumor specimens." (PMID 34112144, 2021). "Furthermore, we elucidated the action mechanisms of ETS1 as a tumor suppressor not only by directly activating down-stream targets linked with tumor cell proliferation/growth but also trans-activation of other tumor suppressor genes, such as ADAMTS9, TXNIP, STAT5A, and NOTCH1." (PMID 32477936, 2020). "ADAMTS9 exerts its tumour suppressor activity by inhibiting cell proliferation, colony formation, arresting the cell cycle, inducing apoptosis, suppressing angiogenesis and suppressing EMT." (PMID 29193730, 2018). "Ectopic expression of ADAMTS9 in tumor cells induced significant growth suppression, cell cycle arrest at the G0/G1 phase, enhanced apoptosis and reduced cell migration and invasion." (PMID 29193730, 2018). "The results showed methylation of the majority of CpG sites in BT549 cells, which was removed after treating the cells with Aza and TSA, further confirming tumour‐specific methylation of the ADAMTS9 CGI." (PMID 29193730, 2018). "The results showed that 10 of 11 (90.1%) tumours had lower ADAMTS9 mRNA expression compared to their paired surgical margin tissues (P < 0.001)." (PMID 29193730, 2018). "Intriguingly, ADAMTS9 inhibits tumor growth by blocking the mTOR pathway, which has long been known to be associated with aging." (PMID 28244876, 2017). "ADAMTS9 functions as a tumor suppressor through decreasing cell proliferation and inhibiting angiogenesis via regulating AKT/mTOR pathway." (PMID 28503860, 2017). "This study demonstrates that ADAMTS9 is a tumor suppressor and regulates cancer partly through Akt pathway independent of its role in angiogenesis." (PMID 24213506, 2012). "They observed an increase in corneal neovascularization and tumor vascularization in Adamts9+/− mice compared to wild type mice." (PMID 24213506, 2012). "When ADAMTS9 was mapped to chromosome 3p14.2 it was suspected to be involved in tumor suppression as it shared the same region that was involved in chromosomal translocations in common hereditary renal cell carcinomas." (PMID 24213506, 2012). "Taken together, ADAMTS9 is a potent tumor suppressor gene that is epigenetically silenced in a wide range of cancers." (PMID 24213506, 2012). "However, there is little information about the activity of ADAMTS-9 versicanase in the tumor microenvironment." (PMID 39682243, 2024).
tumor (continued). "In addition, when comparing CMT and CSS, the relationship between ADAMTS-9 and less aggressive tumor behavior becomes more evident." (PMID 39682243, 2024). "In addition, ADAMTS9 has been identified to inhibit tumor progression by regulating the PI3K/AKT/mTOR pathway." (PMID 35574388, 2022). "As a tumor suppressor, RNF180 could restore the activity of some tumor-related genes, including ADAMTS9, and played a crucial role in impairing lymphatic involvement of GC cells." (PMID 33931579, 2021). "ADAMTS9 can also inhibit tumor progression by inhibiting angiogenesis." (PMID 32884571, 2020). "ADAMTS9 methylation was detected in 130/219 (59.4%) of BC tissues, and 4.5% (2/44) of paired adjacent tissues, but not in normal epithelial tissues, highlighting the relevance of tumour‐specific ADAMTS9 methylation." (PMID 29193730, 2018). "We found that the inhibition of tumor migration and invasion by ADAMTS18 are associated with deregulation of AKT and NF‐κB signaling pathway, in which AKT pathway was in line with the findings in ADAMTS9, another member of the same subgroup 6." (PMID 28503860, 2017). "In addition, ADAMTS9 acts as a tumor suppressor by directly inhibiting tumor cell proliferation and inducing tumor cell apoptosis through inhibition of Akt signaling pathway." (PMID 24213506, 2012). "Outcome in all three cancers reconfirmed the tumor suppressor role of ADAMTS9." (PMID 24213506, 2012). "A survival analysis was conducted based on the ADAMTS6, ADAMTS9 and ADAMTS12 expression in tumor tissue using data gathered from the external Kaplan–Meier Plot database." (PMID 38339175, 2024). "The second aim of the project was to evaluate the expression of the ADAMTS6, ADAMTS9 and ADAMTS12 genes in the tumor tissue samples." (PMID 38339175, 2024). "Based on data collected from the UALCAN database, differences in the ADAMTS6, ADAMTS9 and ADAMTS12 gene expression levels were also assessed between tumor tissue and normal tissue." (PMID 38339175, 2024). "ADAMTS9 is the most widely conserved member of the ADAMTS family and has recently been reported to be a novel tumor suppressor that is downregulated in several varieties of human cancer." (PMID 28244876, 2017). "However, studies have suggested that the tumor-suppressive effects of ADAMTSs are linked to the deactivation of proliferation or invasion pathways, including inhibition of the ERK pathway by ADAMTS8, ADAMTS12, and ADAMTS15; and of the AKT/mTOR pathway by ADAMTS9." (PMID 27542224, 2016). "HYP also exerts anti-metastatic and anti-tumor effects even in the absence of light, while light activation promotes the expression of genes such as ADAMTS9, further suppressing cancer progression." (PMID 41226910, 2025). "We further verified the expression levels of ADAMTS9, ENTPD1, FRMD3, PRR15, AKAP12 in THCA, and the results of GEPIA database showed that ENTPD1, FRMD3, PRR15 were obviously increased in tumor tissues (n=512) compared with normal tissues (n=337), and the difference was statistically significant." (PMID 35756646, 2022). "We examined ADAMTS9 mRNA levels in 16 pairs of GC and adjacent normal tissues, showing that ADAMTS9 mRNA levels were markedly decreased in nine tumor tissues compared with non-tumor counterparts." (PMID 33931579, 2021). "Overexpression of ADAMTS9 suppressed both ESCC and NPC tumor growth in vivo." (PMID 24213506, 2012). "ADAMTS9 was down-regulated in ESCC cell lines and primary tumor tissue samples." (PMID 24213506, 2012). "However, the mRNA levels of ADAMTS9 in tumor tissues were not statistically different from those in normal tissues." (PMID 35756646, 2022).
cancer (27 papers, 2007 to 2025). A tumor composed of atypical neoplastic, often pleomorphic cells that invade other tissues. "Several well-known cancer-associated genes (including ADAMTS9, CCND1, HIC1, etc.)exhibited consistently disrupted methylation and expression statuses in the majority of the bladder urothelium cancer samples." (PMID 22140553, 2011). "aberrant expression of ADAMTS9 in a variety of cancers is closely associated with cancer proliferation, invasion, migration, and inhibition of apoptosis, and has been shown to mediate in various ways cancer development, such as regulating miRNAs and activating classical signaling pathways in cancer." (PMID 37872487, 2023). "Genes potentially associated with cell migration and cancer metastasis included CNTN5, FN1, Integrin Subunit Beta 6 (ITGB6), EPHB1, Unc-5 Netrin Receptor D (UNC5D), SDK1, RADIL, LRRC7, PCDH11X, and ADAMTS9." (PMID 39770638, 2024). "EVs exclusively contained PLEKHG2 (nucleotide-binding protein), GPR68 (a proton sensing G protein-coupled receptor 68), POU4F2, ADAMTS9, and Let-7 microRNA precursor, which are involved in cell development, signal transduction, and cancer metastasis." (PMID 35663013, 2022). "ADAMTS9 suppresses cancer both directly through inhibition of cancer cell proliferation, induction of cancer cell apoptosis and indirectly by inhibiting angiogenesis." (PMID 24213506, 2012). "However, ZG16 and ADAMTS9, which have been ascribed roles in the control of cancer development, were also down-regulated." (PMID 32366023, 2020). "ADAMTS1 and ADAMTS9 have been found to be epigenetically silenced in diverse malignant tumors." (PMID 30081852, 2018). "ADAMTS-9 has recently been reported to have an anti-angiogenic function in cancer." (PMID 23947778, 2013). "ADAMTS9, a thrombospondin metalloproteinase, is a member of the ADAM-TS family, which controls organ shape during development, inhibit angiogenesis, and are implicated in cancer." (PMID 17201907, 2007). "Besides, we identified several canonical cancer-associated genes that were not enriched in the significantly disturbed pathways, such as ADAMTS9, HIC1, RASAL1, in both the methylation statuses and expression data." (PMID 22140553, 2011). "The bioinformatic analyses found the presence of a distinct DMR pattern among ADAMTS6, ADAMTS9, and ADAMTS12 to be a useful tool for distinguishing normal cells from cancer cells." (PMID 39940703, 2025). "Different transcript levels of ADAMTS6, ADAMTS9, and ADAMTS12 are observed in various types of cancer, which points to the problematic part played by these proteases in the pathogenesis of proliferative diseases." (PMID 39940703, 2025). "The differential methylation region (DMR) pattern demonstrated by ADAMTS6, ADAMTS9, and ADAMTS12 is a useful tool for distinguishing normal from cancer cells." (PMID 39940703, 2025). "Bioinformatic analysis revealed a decrease in the expression of the ADAMTS9 gene and an increase in ADAMTS12 expression in the cancer tissue of patients with NSCLC compared to normal tissue." (PMID 38339175, 2024). "ADAMTS9 belongs to the ADAMTS protein family and is frequently downregulated as a result of promoter hypermethylation in a variety of human cancers." (PMID 35574388, 2022). "The gene expression data available in the databases indicated differences between tumors and normal tissue with regard to the regulation of ADAMTS6, ADAMTS9, and ADAMTS12, which may be related to their different roles in cancer pathogenesis." (PMID 39940703, 2025). "Adamts9 has not been directly studied for a role in lipoprotein metabolism but has been shown to be a suppressor of mammalian target of rapamycin pathway in cancer cell lines." (PMID 37944753, 2023). "ADAMTS9 belongs to the ADAMTS (a disintegrin and metalloproteinase with thrombospondin motifs) protein family, and its expression is frequently silenced due to promoter hypermethylation in various human cancers." (PMID 33931579, 2021).
cancer (continued). "Hypermethylation of ADAMTS9 and RERG were associated with risk of CRC only without a family history of cancer." (PMID 27453436, 2016). "A canonical cancer pathway involving the NFkB complex is central to this network, which is predicted to activate (denoted by orange relationship lines) various genes upregulated in the dataset, including the transcription regulator CITED4, peptidase ADAMTS9, and kinase PIM3." (PMID 32414099, 2020).
adenocarcinoma (2 papers, 2024 to 2025). A common cancer characterized by the presence of malignant glandular cells. "This correlation was particularly pronounced in the adenocarcinoma subtype (p < 0.0001), where the survival of patients with a higher ADAMTS9 gene expression (127 months) was almost twice as long as that of individuals with lower expression (76 months)." (PMID 38339175, 2024).
kidney disease (2 papers, 2023 to 2024). "Mutations in ADAMTS9 cause nephronophthisis-related ciliopathies (NPHP-RC), which are characterized by multiple developmental defects and kidney diseases." (PMID 37035301, 2023).
cardiac diseases (1 paper, 2020). "It is noteworthy that two recently discovered Mendelian disorders arising from ADAMTS9 and ADAMTS19 broadened the spectrum of affected organs (renal and cardiac diseases, respectively) that have never been associated with six previously identified ADAMTS genes responsible for Mendelian disorders." (PMID 32183147, 2020).
infection (1 paper, 2024). The state of being infected such as from the introduction of a foreign agent such as serum, vaccine, antigenic substance or organism. "The top upregulated genes in KSHV lytic and mixed infection spots are predicted to encode proteins that regulate angiogenesis including ADAMTS9, KDR and PGF, endothelial cell development including KDR and STC1, and cell-substrate adhesion, SPRY4, ITGA1, ADAMTS9, KDR, MMP12." (PMID 39386738, 2024).
ADAMTS9 also shares sentences with these, for which no sentence is quoted: Obesity (6 papers); lung fibrosis (3); cardiovascular disease (2); hepatocellular carcinoma (2); Joubert syndrome (2); prostate carcinoma (2); rheumatoid arthritis (2); Alzheimer disease (1); central nervous system disorder (1); cervical cancer (1); cognitive decline (1); Cognitive impairment (1); endometrial polyp (1); endometriosis (1); endothelial dysfunction (1); esophageal tumors (1); glomerulopathy (1); Headache (1); Hepatic steatosis (1); Hydrocephalus (1); hyperprolactinemia (1); hypertriglyceridemia (1); intervertebral disc degeneration (1); invasive breast carcinoma (1); knee osteoarthritis (1); liver cancer (1); lung adenocarcinoma (1); Mendelian diseases (1); metabolic disease (1); multiple myeloma (1).
A further 9 diseases each share a sentence with ADAMTS9 in 1 paper.